EGFR (epidermal growth factor receptor)
Diseases named in the same sentence as EGFR in open-access papers (continued):
Sharing a sentence is not in itself a finding about the gene and the disease.
lung cancer (continued). "Epidermal growth factor receptor (EGFR) belongs to the RTK protein family and is dysregulated in the majority of malignant tumors, such as lung cancer, colorectal carcinoma, breast and head/neck cancers." (PMID 25654224, 2015). "Treatment with EGFR tyrosine kinase inhibitor (TKI), e.g. gefitinib and/or erlotinib, in advanced lung cancer has proven itself effective." (PMID 25886900, 2015). "In human lung cancer cells such as A549 and NCI-H1975, which harbor constitutive active Ras and EGFR mutants, respectively, magnolin suppressed wound healing and cell invasion as seen by a Boyden chamber assay." (PMID 26253302, 2015). "Overexpression of epidermal growth factor receptor (EGFR) is observed in various malignancies, including lung cancer." (PMID 25532027, 2015). "We find that higher levels of EGFR relative to MET, another RTK with oncogenic properties in lung cancer, correlate with prolonged PFS to EGFR TKIs." (PMID 26439803, 2015). "In lung cancer, HGF has also been shown to interfere with EGF tyrosine kinase activation, which in turn results in induced resistance to EGFR inhibitor therapies." (PMID 26310485, 2015). "Gefitinib, approved for lung cancers, is a tyrosine kinase inhibitor (TKI) that targets the adenosine triphosphate binding site in the cytoplasmic domain of EGFR." (PMID 25501339, 2015). "Consequently, further genetic and molecular studies using next-generation sequencing explored whether MPM involving lung cancer share common molecular targets, such as EGFR, Kirsten rat sarcoma viral oncogene homolog (KRAS) and anaplastic lymphoma kinase (ALK) to improve therapeutic outcome." (PMID 26466785, 2015). "Recently, we reported about the ligand-dependent EGFR activation in both H3122 CR1 cells and SNU-2535, a lung cancer cell line derived from a patient who had developed acquired resistance to crizotinib." (PMID 26517679, 2015). "A multi-marker panel measuring mRNA expression of CCN1, EGFR, FGF19, FRS2, and GREB1 in saliva, differentiated patients with lung cancer from controls with a sensitivity of 93.75 % and specificity of 82.8 %." (PMID 26603430, 2015). "Recent advances added EGFR (Epidermal Growth Factor Receptor) and ALK (Anaplastic Lymphoma Kinase) as biomarkers that should be tested for in patients with advanced lung cancer." (PMID 25784483, 2015). "Delineating the function of IL-8 in EGFR TKI resistance, we showed that IL-8 is capable of driving stem cell-like characteristics in lung cancer cells." (PMID 25871388, 2015). "Previous studies showed that activation of IGF1R is involved in EGFR-TKIs resistance in NSCLC cell lines and in lung cancer patients." (PMID 26554308, 2015). "A recent study demonstrates that inhibition of EGFR by erlotinib, an EGFR inhibitor results in activation of the STAT3 signaling in lung cancer cells." (PMID 25669984, 2015). "The ability to alter EGFR-TKIs responses makes miRNAs as potential predictive biomarkers for EGFR-TKIs in lung cancer treatment, and several miRNAs could be served as biomarkers to predict response to EGFR-TKIs in lung cancer patients have been recently well documented." (PMID 26273639, 2015). "For example, the amplification and overexpression of epidermal growth factor receptor (EGFR) and the under-expression of dual specificity phosphates 4 (DUSP4) served as effective prognostic biomarkers in lung cancer." (PMID 24650256, 2014). "Both miR-143 and miR-145 are able to inhibit cell growth, proliferation and migration of lung cancer cells through the repression of c-MYC, EGFR, NUDT1 and OCT4." (PMID 25593996, 2014). "In lung cancer cells, IGF1R and EGFR signaling play key roles and have been suggested as major factors upstream of the PI3K/AKT pathway." (PMID 25344917, 2014). "The method was applied to the A549 lung cancer cell line, and we identified specific kinases known to have an important role in this type of cancer (TGFBR2, EGFR, PHKG1 and CDK4)." (PMID 24961498, 2014).
lung cancer (continued). "In the Lung1 cohort, when grouped by age, EGFR/KRAS/ALK alteration status, and smoking history, N39 further stratified lung cancer patients with significant differences in survival." (PMID 25146220, 2014). "EGFR, VEGFR, Akt, and NF-kB have become the important targets against a variety of cancer including lung cancer cells." (PMID 25138052, 2014). "Because no large Caucasian series was tested for EGFR genetic heterogeneity, we addressed this question in clinical testing conditions thanks to a French nationwide EGFR mutation characterization program in advanced lung cancer (National Cancer Institute, INCa)." (PMID 24885034, 2014). "For example, low expression of miR-145 is related to the colorectal cancer, yet also reported in lung cancer as CRC and lung cancer share epidermal growth factor receptor (EGFR) property." (PMID 24936152, 2014). "Presently, there are various chemotherapeutics that are being utilized in the treatment of lung cancer, including FDA approved drugs (DDP, paclitaxel, docetaxel, gemcitabine, and EGFR-TKIs), natural compounds (curcumin), and small organic compounds (PRIMA-1)." (PMID 24999473, 2014). "However, despite an almost universal presence of EGFR in NSCLC tumors, the therapeutic inhibition of EGFR by gefitinib and erlotinib results in significant tumor regression in only 10–20% of patients, again indicating the variation in the molecular pathogenesis of the different types of lung cancer." (PMID 25364399, 2014). "HSP90 inhibitors have shown activity in EGFR mutant lung cancer after the development of resistance, in ALK-rearranged tumors and more recently in EGFR wild type adenocarcinoma when combined with chemotherapy." (PMID 25505733, 2014). "Collectively, our data showed that CUL4A promotes NSCLC cell proliferation through EGFR-AKT pathway and high level of CUL4A expression sensitizes lung cancer cells to erlotinib." (PMID 25413624, 2014). "The results indicate that the mRNA expression of CK19, EGFR and LUNX in the peripheral blood is of significant clinical value for the diagnosis of micrometastasis and the prognosis of lung cancer." (PMID 24396405, 2014). "The epidermal growth factor receptor (EGFR), one of the most studied tyrosine kinase receptors, is a prototypic cell-surface receptor that can be targeted by drugs against lung cancer." (PMID 24497964, 2014). "For HER1/EGFR, we showed a down-regulation of one of the transcripts (last exon > e20) in SRSF2-over-expressing H358 lung cancer cells in comparison to H358 control cells." (PMID 24428911, 2014). "In this study, we showed that EGFR interacts with and phosphorylates GPRC5A, leading to inactivation of the tumor suppressive function of GPRC5A in lung cancer cells." (PMID 25311788, 2014). "Gefitinib is a selective EGFR-TKI and was the first approved for clinical use as an orally administered drug for patients with lung cancer." (PMID 24658031, 2014). "EGFR testing may be performed in selected cases of squamous tumors, guided by clinical criteria (e.g., young age, minimal, or remote smoking) and especially in the setting of more limited lung cancer specimens (biopsy, cytology) in which an adenocarcinoma component cannot be completely excluded." (PMID 25538894, 2014). "In models more closely reflecting lung cancer, afatinib also inhibited survival of NSCLC cell lines expressing L858R/T790M or EGFR E746_A750del (HCC827); while the latter was also sensitive to erlotinib, the former was erlotinib-resistant." (PMID 24643470, 2014). "Therefore, solely targeting EGFR phosphorylation may not be sufficient to inhibit EGFR-mediated signaling in lung cancer without EGFR mutations, indicating that we do not fully understand EGFR signaling in lung cancer." (PMID 24658031, 2014). "Together, these results indicate that endogenous EGFR can phosphorylate GPRC5A at four identified tyrosine residues (Y317, Y320, Y347 and Y350) in response to EGF stimulation in the lung cancer H1792 cells." (PMID 25311788, 2014).
lung cancer (continued). "Four of these markers (BRAF, EGFR, LZTS1, and FGF19) have been directly correlated with lung cancer development and progression." (PMID 25397880, 2014). "The oncogenic receptors in lung cancer cells, including insulin-like growth factor 1 receptor (IGF-1R), TGF-beta receptor type-1 (TGFBR1), and epidermal growth factor receptor (EGFR), are direct targets of miR-133a." (PMID 24816813, 2014). "A previous in vitro study using a lung cancer cell line reported ADCC with cetuximab and suggested a correlation between EGFR expression levels and the magnitude of ADCC." (PMID 24137455, 2013). "We next focused our attention on a second round of TAP, to walk the interactome by using proteins predominately found in lung cancer cell line and AALE TAP data as secondary baits, with a goal to build a larger interactome centered on mutant EGFR." (PMID 24189400, 2013). "Other well defined markers of lung cancer are the Kirsten rat sarcoma viral oncogene homolog (KRAS) and Epidermal growth factor receptor (EGFR)." (PMID 23384026, 2013). "TK inhibitors (TKIs), particularly proteins that target the epidermal growth factor receptor pathway (EGFR), have a promising therapeutic value for the treatment of lung cancer." (PMID 24146957, 2013). "We investigated the activation and function of EGFR in the A549 and HK2 lung cancer cell lines, which contain 3 and 6 copies of ErbB1, respectively." (PMID 23631593, 2013). "Arsenic species directly modulate several oncogenic pathways - most notably the EGFR, PI3K/AKT and the NRF2/KEAP1 pathways - and these specific pathways possess actionable targets for therapy in lung cancer." (PMID 23510327, 2013). "The erlotinib-resistant lung cancer cell line H1650 (H1650ER), originally derived from the parental H1650 cell line, demonstrated an increased dependency on EGFR signaling for growth." (PMID 23520479, 2013). "We first investigated the growth inhibition effect of EGFR-TKI treatment in human tongue and lung cancer cells, using MTT assay." (PMID 23592411, 2013). "In the present study, we found that centrocyte/centroblast marker 1 (CM1), previously reported as a possible apoptosis inducer of B lymphoma cells, is expressed on both A549 with wild-type EGFR and HCC827 with mutant EGFR lung cancer cells." (PMID 23232551, 2013). "Recent clinical trials have shown that progression-free survival (PFS) in patients with EGFR mutant lung cancer is prolonged by treatment with a reversible EGFR-TKI and the irreversible EGFR-TKI afatinib, which was designed to covalently bind to EGFR." (PMID 24386407, 2013). "We also investigated the combination of EGFR TKIs (gefitinib, erlotinib or afatinib) or the monoclonal EGFR antibody cetuximab, with the c-MET inhibitor su11274 in the same set of lung cancer cell lines." (PMID 23527257, 2013). "Erlotinib is an EGFR-specific TKI that has been approved by the Food and Drug Administration to be used as a molecularly targeted drug for lung cancer patients." (PMID 23407898, 2013). "The epidermal growth factor receptor (EGFR) signaling pathway plays a central role in the development and progression of lung cancer." (PMID 23874880, 2013). "In addition to the six EGFR-mutant lines tested above (erlotinib-sensitive and -resistant pairs of PC9, HCC827, and HCC4006 cells), we added one additional engineered HCC827 cell expressing exon 19 deletion E746-A750 plus T790M, as well as 10 lung cancer cell lines lacking EGFR mutations." (PMID 24189400, 2013). "The aim of this study was to analyze the mechanisms of acquired resistance to EGFR-TKI and its frequency in Korean patients with lung cancer." (PMID 24369725, 2013). "EGFR tyrosine kinase inhibitors (EGF-TKI) intercept EGFR-mediated downstream signaling pathways (such as PI3K-AKT) via de-phosphorylation of Her3, while some lung carcinoma cell lines acquire resistance via amplification of MET." (PMID 23296269, 2013).
lung cancer (continued). "As MUC1 potentiates BPDE-induced activation of EGFR, it is likely that MUC1 contributes to lung cancer development at least in part through EGFR-mediated cell survival pathways such as Akt and ERK." (PMID 22457794, 2012). "A great deal of progress has been made in the target therapy for nonsmall cell lung cancer (NSCLC), largely owing to the development of small-molecular inhibitors, such as epidermal growth factor receptor (EGFR) and ALK." (PMID 23342255, 2012). "Engelman and colleagues demonstrated that crosstalk between EGFR and Met was mediated by phosphorylation and signaling from HER3 to Akt in lung cancer cell lines and that this crosstalk mediated resistance to EGFR TKIs." (PMID 22788954, 2012). "In summary, we have discussed a line of novel molecular mechanisms and therapeutic targets for curcumin, including EGFR degradation, miRNA, autophagy and CSC, in human lung cancer." (PMID 22489192, 2012). "In addition, because combined chemoprevention targeting more than one oncogenic protein could potentiate the cancer preventive activity and reduce toxicity, it would be interesting to determine if a regime targeting both MUC1 and EGFR achieves more effective prevention against lung cancer." (PMID 22457794, 2012). "In lung cancer it has been shown that, due to its cross reactivity/compensation effect with EGFR, HGFR/c-MET gene amplification can confer resistance to EGFR-targeting drugs." (PMID 22606042, 2012). "Increased gene copy number of EGFR and overexpression/amplification of HER2 pose the precondition for anti-EGFR and anti-Her2 therapy in breast, colorectal and lung cancer." (PMID 22240798, 2012). "Genetic alterations of EGFR (exons 18, 19, 20, and 21) are important for predicting the efficacy of personalized medicine such as IRESSA in patients with lung cancer." (PMID 22685658, 2012). "Our data suggest that targeting the EGFR indirectly by inhibiting its cytoplasmic activators, the cytohesins, has the potential to improve the treatment of primarily EGFR-TKI resistant lung cancers." (PMID 22815959, 2012). "Interestingly, the subclonal populations of EGFR mutant tumor cells with and without the EGFR T790M allele may coexist in an EGFR mutant lung cancer with acquired EGFR TKI resistance." (PMID 22970367, 2012). "Therefore, EGFR-, miRNA-, autophagy- and cancer stem cell-based therapy in the presence of curcumin might be promising mechanisms and targets in the therapeutic strategy of lung cancer." (PMID 22489192, 2012). "Most of these mutations were frequently observed in certain focused pathways, e.g., four genes from the EGFR-RAS-RAF signaling pathway, EGFR, KRAS, HER2, and BRAF, behave in a mutual exclusive fashion in lung cancer." (PMID 22624051, 2012). "More and more novel potential biomarkers for lung cancer have been discovered, such as SAA, DDH, EGFR, Mig-6." (PMID 22615840, 2012). "We evaluated in vitro the effects of C75 and EGCG on fatty acid metabolism (FASN and CPT enzymes), cellular proliferation, apoptosis and cell signaling (EGFR, ERK1/2, AKT and mTOR) in human A549 lung carcinoma cells." (PMID 22769244, 2012). "Here we compare the effects of C75 and EGCG on lipogenesis (FASN activity), fatty acid oxidation (CPT activity), cellular proliferation, induction of apoptosis and cell signaling (EGFR, ERK1/2, AKT and mTOR) in A549 lung carcinoma cells." (PMID 22769244, 2012). "First, we compared the expression of six molecular biomarkers (MDR-1, LRP, RRM-1, EGFR, ERCC-1, and BRCA-1) in the primary lung carcinoma and the metastatic lymph nodes of patients with the two subtypes of NSCLC." (PMID 22890830, 2012). "To examine the roles of MET, EGFR, HER2, HER3, and RET in lung cancer cells with MET amplification, we first investigated the effects of PHA-665752, gefitinib, lapatinib, and vandetanib on cell proliferation and survival." (PMID 21847121, 2011).
lung cancer (continued). "For example, EGFR, which overexpressed in 40–80% of NSCLC, is an important up-stream regulator of PI3K/Akt and RAS/RAF/MEK/ERK pathway in lung cancers." (PMID 21283735, 2011). "With the use of an RTK array, we found that EBC-1 and H1993, two human lung cancer cell lines with MET amplification, exhibited a high level of tyrosine phosphorylation of MET, EGFR, HER2, HER3, and RET under conditions of serum deprivation." (PMID 21847121, 2011). "It is thus possible that trans-phosphorylated EGFR, HER2, HER3, and RET act as scaffold proteins to promote downstream signalling of MET in lung cancer cells with MET amplification." (PMID 21847121, 2011). "Not surprisingly, EGFR mutations have been identified in several types of cancer and it is a target of many anticancer therapies, including small-molecule TK inhibitors (e.g., gefitinib and erlotinib for lung cancer) and monoclonal antibodies (e.g., cetuximab and panitumumab for colon cancer)." (PMID 21943394, 2011). "Though whether EGFR mutation found in metastatic lymph nodes is accordance with that of the primary tumor is still unknown, however, molecular biological information provided by EBUS-TBNA is evidently of great value and maybe it can guide targeted therapy for advanced lung cancer patients." (PMID 21418631, 2011). "High expression of epidermal growth factor receptor (EGFR) protein was observed in several types of cancer including breast, bladder, colon and lung carcinomas." (PMID 21211062, 2011). "Previous studies already demonstrated that CISH is a useful technique for the detection of EGFR and HER2 gene amplification in breast and lung cancer FNAC both in conventional and in monolayered smears obtained by liquid based cytology." (PMID 20843314, 2010). "Another potential mechanism of EGFR inhibitor resistance is inflammation, such as by release of the inflammatory cytokine prostaglandin E2, which in lung cancer cells induced phosphorylation of MAPK, indicating a bypass of EGFR activation." (PMID 20037743, 2010). "The activity of the epidermal growth factor receptor (EGFR) is frequently elevated in lung cancer, and inhibition of EGFR through the TKI erlotinib can extend survival in patients with advanced lung cancer refractory to chemotherapy." (PMID 20976048, 2010). "In lung cancer, gene copy number assessed by fluorescence in situ hybridization (FISH) has been reported to indicate sensitivity to EGFR inhibition." (PMID 20037743, 2010). "The overexpression of EGFR and HER-2, which has been observed in a significant number of lung cancer patients, offers an opportunity to block these tyrosine kinase receptors with targeted drugs." (PMID 20459769, 2010). "It has recently been shown that therapies targeting the epidermal growth factor receptor (EGFR) provided clinical benefit in patients with head and neck, pancreatic, colorectal, and lung cancers." (PMID 21073737, 2010). "Four lung cancer cell lines (H292, H441, H358 and HCC827) were briefly exposed to erlotinib, an inhibitor of EGFR, or dasatinib, a SRC family kinase inhibitor that inhibits multiple tyrosine and serine/threonine kinases." (PMID 20976048, 2010). "Studies have shown that EGFR and HER-2 protein overexpression is present in 43-89%, and 30-40% lung cancer specimens, respectively." (PMID 20459769, 2010). "Validation of the model in a panel of 65 lung cancer cell lines perturbed using PI3K and EGFR/ERBB2 signaling pathway inhibitors revealed general rules of the signaling pathway topology downstream of genetically altered EGFR and ERBB2 kinases." (PMID 20111714, 2010). "Lastly, biomarker studies from the Iressa Pan-Asia Study (IPASS) and the first-line Cetuximab in lung cancer (FLEX) trials will be reviewed; such trials managed to reveal predictive factors for inhibitors of epidermal growth factor receptor (EGFR)." (PMID 20433767, 2010).